BRCA1 (BRCA1 DNA repair associated)
Diseases named in the same sentence as BRCA1 in open-access papers (continued):
Sharing a sentence is not in itself a finding about the gene and the disease.
breast cancer (continued). "Germline mutations in the BRCA1 and BRCA2 genes are identified in about one quarter of the families with breast cancer." (PMID 19607694, 2009). "BRCA1 mutations are associated with female breast and ovarian cancer, while BRCA2 mutations are rather associated with female and male breast cancer and to a lesser extent with ovarian cancer." (PMID 19352458, 2009). "Within the training set, our approach enables a correct classification of all BRCA1 mutants considered, while only 12 sporadic breast cancers are misclassified." (PMID 19695104, 2009). "For example, in some forms of breast cancer, the human BRCA1 gene generates two isoforms due to translation from a first AUG codon and a second, in-frame." (PMID 19730687, 2009). "Our data demonstrate that patients with BRCA1/2 breast cancers harboring any of the three MDM2 SNP309 had similar cancer onset ages." (PMID 19226467, 2009). "Mutations in two major genes, BRCA1 and BRCA2, account for up to 30% of families with hereditary breast cancer." (PMID 19352458, 2009). "Before elaborating on the Brca1 conventional and conditional mouse models that have been generated to date, we will discuss the characteristics of human BRCA1-related breast cancer in more detail." (PMID 19904273, 2009). "In the BRCA1-positive group, the rate of patients who developed bilateral breast cancer accounted for 27.1% (13 cases)." (PMID 18405391, 2008). "The overall similarity of gene expression profiles among five original Brca1 mammary tumors was assessed by pairwise correlations of microarray log-ratios based on 15,781 probes with reported values in at least 75% of samples." (PMID 18394172, 2008). "Methylation of the BRCA1 promoter has been shown to occur in approximately 20% of breast cancer patients." (PMID 18269736, 2008). "Nonetheless, the potential modulation by CHEK2 of both BRCA1 and BRCA2 would point to an important function for this checkpoint kinase in the DNA damage repair pathways implicated in the development of breast cancer." (PMID 18797466, 2008). "Some studies have indicated that BRCA1 mRNA expression is lower in basal-like sporadic cancers, and in approximately 30% of sporadic breast cancers." (PMID 18950515, 2008). "The breast-cancer gene BRCA1 is a well-known empirical case of synonymous rate variation, since Hurst and Pál conducted a sliding-window analysis to compare the human with the dog and the mouse with the rat genes." (PMID 19015730, 2008). "Hereditary artifacts in BRCA1 gene have a significant contributory role in familial cases of breast cancer." (PMID 18759965, 2008). "We examined the peripheral blood leukocyte DNA of seven breast cancer cases (KCF1 to KCF7) (ages of onset ranging from 35 to 51 years) for BRCA1 methylation." (PMID 18269736, 2008). "The profound similarities between hereditary BRCA1-related breast cancers and basal-like breast cancers suggest a fundamental defect in the BRCA1 pathway in sporadic basal-like breast cancers." (PMID 18950515, 2008). "Further studies involving a screening of entire coding region of BRCA1 is required to explore the merits of genetic diagnosis and counseling in breast cancer patients." (PMID 18759965, 2008). "We included in the study ten familial breast cancer samples, which carried sequence changes in BRCA1 or BRCA2, that are believed to be of little clinical significance." (PMID 18497862, 2008).
breast cancer (continued). "BRCA1 and BRCA2 account for the majority of the known familial breast cancer risk, however, the impact of other cancer susceptibility genes largely remains to be elucidated." (PMID 18706089, 2008). "Another example of the commonly mutated tumour suppressor genes are BRCA1 and BRCA2, which are the only known high penetrance genes involved in breast cancer susceptibility." (PMID 19506729, 2008). "Mutations in the high-risk breast cancer-susceptibility genes BRCA1 and BRCA2 account for approximately 15% of this excess familial risk." (PMID 18349832, 2008). "BRCA1 and BRCA2 gene mutation carriers are at risk of developing breast cancer earlier than other patients." (PMID 18405391, 2008). "In BRCA2 IVS16-2A>G families we found a breast cancer incidence of 24.6% (15/61), which is higher than what is seen in the two types of BRCA1 families." (PMID 18783588, 2008). "BRCA1 and BRCA2 mutations are highly penetrant with a lifetime risk of 46–87% and 26–84% respectively of developing breast cancer by the age of 70 years for mutation carriers." (PMID 18662409, 2008). "Inherited mutations in the genes BRCA1 and BRCA2 increase risk of breast cancer and contribute to a proportion of breast cancer families." (PMID 18497862, 2008). "Numerous studies have reported that basal CKs are more frequently positive in BRCA1 tumours than in sporadic breast cancers." (PMID 18275599, 2008). "In this study, a full mutation analysis of the ATM gene was carried out in patients from 137 Chilean breast cancer families, of which 126 were BRCA1/2 negatives and 11 BRCA1/2 positives." (PMID 18433505, 2008). "Mutations in BRCA1 and BRCA2 account for a considerable proportion of these familial breast cancer cases, with the average cumulative risk in BRCA1 and BRCA2 mutation carriers by age 70 years estimated at 65% and 45%, respectively." (PMID 18497862, 2008). "In choosing this, the overall male breast cancer incidences over the BRCA1, BRCA2 and polygenic effects were constrained to agree with the population incidences." (PMID 18349832, 2008). "A total of 105 distinct BRCA1 variants (including 32 DDCVs) and 157 distinct BRCA2 variants (including 27 DDCVs) were identified in the 1,469 breast cancer patients." (PMID 18284688, 2008). "The histopathological features of breast tumours from patients with BRCA1 and BRCA2 mutations differ from each other and from sporadic breast cancers." (PMID 18182994, 2008). "Rather than an allelic methylation as has previously been reported for MLH1, a mosaic level of BRCA1 methylation has been identified in the somatic tissues of some breast cancer patients." (PMID 18269736, 2008). "About 10% of breast cancer cases that are due to BRCA1 or BRCA2 mutations are considered familial, but the majority of breast cancer cases are sporadic." (PMID 19506729, 2008). "BRCA1 is also an AR coactivator that has been demonstrated to enhance AR transactivation in prostate and breast cancer cell lines with a synergistic effect with other p160 coactivators." (PMID 18673534, 2008). "Inherited heterozygous BRCA1 and BRCA2 defects have been associated with an enhanced risk of early onset breast cancer." (PMID 18197258, 2008). "BRCA1 mRNA expression was significantly decreased in TNBCs compared to luminal subtype breast cancers." (PMID 18950515, 2008). "Given the apparent heterogeneity of Brca1 mammary tumors, we examined the extent to which serial transplantations of individual tumors affect gene expression." (PMID 18394172, 2008). "Overall, the BRCA mutation-negative cases had a significantly older mean age of diagnosis of breast cancer than each of the BRCA1 and BRCA2 mutation-positive groups (p = 0.02), as has been observed in previous studies of French Canadian breast cancer families." (PMID 18402691, 2008).
breast cancer (continued). "To date, two main breast cancer susceptibility genes have been identified; BRCA1 and BRCA2 accounting for nearly half of high-incidence breast cancer families and an increased relative risk of breast cancer by 10- to 20- fold." (PMID 18637200, 2008). "The peripheral blood leukocyte DNA of seven age-matched normal controls was examined for BRCA1 methylation for comparison to the breast cancer patients." (PMID 18269736, 2008). "Although the significance of the E3 activity of BRCA1 in the BRCA1 functional network is only partially understood, it is obvious that its activity is crucial in the prevention of a certain subset of breast cancers." (PMID 19007432, 2008). "We have now updated BOADICEA using additional family data from two UK population-based studies of breast cancer and family data from BRCA1 and BRCA2 carriers identified by 22 population-based studies of breast or ovarian cancer." (PMID 18349832, 2008). "In the high-risk families that recruited to the Breast Cancer Linkage Consortium (BCLC) cohort, BRCA1 and BRCA2 mutations were estimated to cause a cumulative lifetime risk of breast cancer at age 70 years of 85–87% and 77–84% respectively." (PMID 18513387, 2008). "Here we demonstrate the artifactual effect of sliding-window analysis through a re-analysis of the breast-cancer gene BRCA1 from mammalian species." (PMID 19015730, 2008). "Currently, there is interest in identifying directed treatments for breast cancer in BRCA1 and BRCA2 carriers." (PMID 18577985, 2008). "Brca1-deficient mouse mammary tumors harbor heterogeneous cancer stem cell populations, and CD44+/CD24- cells also identify human breast cancer stem cells." (PMID 18241344, 2008). "Many studies from the developed world report the prevalence of BRCA1 and BRCA2 mutations of breast cancer to vary from 1.8 – 13.1%." (PMID 18662409, 2008). "The BRCA1 DDCV carriers were substantially more likely to have a first-degree family history of breast cancer or ovarian cancer than the normal/polymorphic BRCA1 carriers (odds ratio = 11.3) after adjusting for the BRCA2 mutation status." (PMID 18284688, 2008). "In our study, patients with BRCA1 gene mutations were tested for the expression of steroid receptors (ERβ, ERα and PgR) and the HER-2 receptor in breast cancer tissue." (PMID 18405391, 2008). "CK14 was significantly associated with BRCA1 mutation but also with BRCA2 and non-BRCA1/BRCA2 groups of cancers, as compared with sporadic breast cancers." (PMID 18275599, 2008). "As a contribution to a tumor development, VCP/p97 has been demonstrated to directly bind to BRCA1 as one of the key regulatory genes in breast cancer pathogenesis." (PMID 18279508, 2008). "We have shown that P-CTD fragments exist in breast cancer cell lines, are stabilized by proteasome inhibition, and depend upon the presence of wild type BRCA1." (PMID 18197258, 2008). "The differences between individual Brca1 tumors prompted us to generate and characterize multiple cell lines from each original mammary tumor." (PMID 18394172, 2008). "For example, the high penetrant breast cancer genes, including BRCA1/2, are thought to explain less than 25% of the familial risk." (PMID 18560565, 2008). "Second, some Brca1-deficient tumors contain CD44+/CD24-/Low cells, previously associated with human breast cancer stem cells, whereas others contain CD133+ cells previously associated with tumors in other organs." (PMID 18241344, 2008). "In vitro studies have shown that physiological doses of genistein (0.5–1.0 μM) upregulate BRCA1 in ER+ human breast cancer cells and in prostate cancer cells." (PMID 18392054, 2008). "It is noteworthy that in our series the average number of breast cancers (BC) per family was twice as much in BRCA2 families (3.3) as compared to BRCA1 families (1.6)." (PMID 18783588, 2008).
breast cancer (continued). "BRCA1 and BRCA2 gene carriers are at increased risk of developing contralateral breast cancer and appear, in the longer term, to have an increased rate of new primary tumours in the affected breast." (PMID 17697367, 2007). "Several genes are known to confer increased susceptibility to breast cancer, including BRCA1 and BRCA2, but it has been estimated that they explain only about 25% of the familial risk and less than 5% of the total breast cancer incidence." (PMID 17997823, 2007). "The primary factors that increase the risk are an inherited mutation of the BRCA1 and/or BRCA 2 genes, a family history of breast cancer, high breast density, and a confirmed biopsy of hyperplasia." (PMID 17472751, 2007). "Study on BRCA1 and BRCA2 mutations in Saudi women older than 40 years with breast cancer concluded that mutations in these genes are likely to contribute to the pathogenesis of familial breast cancer in the Kingdom of Saudi Arabia." (PMID 18053234, 2007). "BRCA1 methylation and abrogation of BRCA1 mRNA has been found in sporadic breast cancers but very rarely in NSCLC." (PMID 17987116, 2007). "An analysis performed among carriers of BRCA1 and BRCA2 mutations, showed a greater incidence of breast cancer in younger birth-cohorts compared with relatives of these women belonging to older generations." (PMID 17488519, 2007). "Low BRCA1 levels in human breast cancers are correlated with tumour progression, increased malignancy and poor prognosis." (PMID 17663789, 2007). "Breast cancer cells carrying wild-type BRCA1, such as MCF-7 and MDA-MB231, were more resistant to cisplatin than BRCA1-mutant HCC1937 cells." (PMID 19690636, 2007). "BRCA1 is involved in numerous essential processes in the cell, and the effects of BRCA1 dysfunction in breast cancer carcinogenesis are well described." (PMID 17697391, 2007). "Similar results were reported for BRCA1 and BRCA2 mutations in Korean women with breast cancer at a young age (< 40 years) and also for BRCA1 mutations in a series of Singaporean Chinese women with early onset (cut-off of 40 years)." (PMID 18053234, 2007). "Metcalf and colleagues have shown that RT actually protects against local recurrences and ipsilateral breast cancer among BRCA1 and BRCA2 carriers." (PMID 17428320, 2007). "The basal subtype is associated with poor clinical outcomes and the subtype observed in BRCA1-related breast cancers." (PMID 17764565, 2007). "These biochemical results led to analysis of the expression of BRCA1 as well as PP1α, β and γ, which has provided unique evidence for their potential deregulation in breast cancer." (PMID 17511879, 2007). "The effect of BRCA1 suppression on the chemosensitivity has previously been studied mainly in breast cancer cell lines." (PMID 19690636, 2007). "Given the critical role that decreased BRCA1 expression has in the development of sporadic breast cancer, the study of mechanisms that can down-regulate this key tumour suppressor are of particular importance." (PMID 17663789, 2007). "In a retrospective cohort study of 1,601 female BRCA1 and BRCA2 mutation carriers we found an association with reported chest X-ray exposure and significantly increased risk of breast cancer (hazard ratio 1.54)." (PMID 17428320, 2007). "There are also reports of mutations in BRCA1 and BRCA2, which affect familial breast cancer occurrence, though their penetrance is low." (PMID 17919326, 2007).
breast cancer (continued). "Cancer risks were similar in BRCA1 and BRCA2 carriers, and by age 70 years breast cancer risk was 56% (95% CI 40–73%), and ovarian cancer risk was 16% (95% CI 6–28%)." (PMID 17213823, 2007). "The two major breast cancer susceptibility genes BRCA1 and BRCA2 are involved in 30% of hereditary breast cancer cases, but the discovery of additional breast cancer predisposition genes for the non-BRCA1/2 breast cancer families has so far been unsuccessful." (PMID 17760956, 2007). "Approximately 3% to 5% of breast cancer is estimated to be due to a dominantly inherited gene, and two breast cancer genes, BRCA1 and BRCA2, account for approximately 85% of families with four or more cases of breast and ovarian cancer." (PMID 18053174, 2007). "Germline mutations in the high-penetrance genes BRCA1 and BRCA2 account for up to 25% of the hereditary forms of breast cancer (BC)." (PMID 17504528, 2007). "All participants had a high quantitative breast cancer risk, defined as ≥ 3.5% over the next 5 years per the Gail or BRCAPRO models, and/or a known BRCA1 or BRCA2 germline mutation." (PMID 16800895, 2006). "We previously showed that I3C stimulates BRCA1 expression in human cervical and breast cancer cells." (PMID 16434996, 2006). "The BRCA1 locus on chromosome 17 co-segregates with breast cancer and is characteristic of families in which both early-onset breast and ovarian cancers occur." (PMID 16507150, 2006). "A large number of distinct mutations in the BRCA1 and BRCA2 genes have been reported worldwide, but little is known regarding the role of these inherited susceptibility genes in breast cancer risk among Indian women." (PMID 17018160, 2006). "In this report we have used data from 810 BRCA1 and BRCA2 mutation carriers from the UK to assess the effect of parity on breast cancer risk." (PMID 17187672, 2006). "Carriers of mutations in the BRCA1 and BRCA2 genes have up to a 90% lifetime risk of developing breast cancer and effective preventative strategies are required for these women." (PMID 16538216, 2006). "As for breast cancer cells, BRCA1 and BRCA2 levels were increased by ⩾2-fold at the lowest dose of I3C (20 μM)." (PMID 16434996, 2006). "To accomplish this task, we stably transfected T47D and MDA-MB-468 breast cancer cells with a carboxyl-terminal truncation mutant of BRCA1." (PMID 16417649, 2006). "Germ-line mutations in genes such as BRCA1, BRCA2, and ATM can cause a substantial increase in risk of breast cancer." (PMID 16945136, 2006). "Genistein caused dose- and time-dependent increases in BRCA1 and BRCA2 protein levels in two oestrogen-responsive breast cancer cell lines (MCF-7 and T47D)." (PMID 16434996, 2006). "On the basis of the BRCA1 breast cancer incidence rates estimated by Antoniou and colleagues, the risk of developing breast cancer by the age of 70 years is 60%." (PMID 17187672, 2006). "We used retrospective data on BRCA1 and BRCA2 mutation carriers from the UK to assess the effects of parity-related variables on breast cancer risk." (PMID 17187672, 2006). "We investigated the distribution and the nature of BRCA1 and BRCA2 germline mutations and polymorphisms in a cohort of 204 Indian breast cancer patients and 140 age-matched controls." (PMID 17018160, 2006). "Parous BRCA1 and BRCA2 mutation carriers were at a significantly lower risk of developing breast cancer (hazard ratio 0.54, 95% confidence interval 0.37 to 0.81; p = 0.002)." (PMID 17187672, 2006). "Mutations in BRCA1 and BRCA2 are present in only 35% to 40% of concentrated family clusters of breast/ovarian cancer; hence it is likely that other 'high-penetrance' breast cancer susceptibility genes remain to be identified." (PMID 16507150, 2006).